CCNB2 (cyclin B2)
Diseases named in the same sentence as CCNB2 in open-access papers (continued):
Sharing a sentence is not in itself a finding about the gene and the disease.
triple-negative breast carcinoma (6 papers, 2021 to 2023). An invasive breast carcinoma which is negative for expression of estrogen receptor (ER), progesterone receptor (PR), and human epidermal growth factor receptor 2 (HER2). "For example, overexpression of CCNB2 is associated with poor prognosis in triple-negative breast cancer." (PMID 36820589, 2023). "CCNB2 was also found to promote cell cycle progression resulting in tumorigenesis in cases of triple-negative breast cancer." (PMID 36900109, 2023). "CCNB2 was highly expressed in human triple-negative breast cancer (TNBC) tissues and correlated with the prognosis and clinical pathological features." (PMID 35360870, 2022). "CCNB2 has been shown to promote the proliferation of triple-negative breast cancer cells in vitro and in vivo." (PMID 35354488, 2022). "Cyclin B2 has been shown to stimulate the proliferation of triple negative breast cancer cells and to alter mitotic spindle checkpoint control leading to the genomic instability seen in cancer." (PMID 34638823, 2021).
COVID-19 (5 papers, 2022 to 2024). A disease caused by infection with severe acute respiratory syndrome coronavirus 2. "In our study, seven genes (BUB1, PRC1, KIFC1, RRM2, CDKN3, CCNB2, and MCM6) were involved in the interaction between COVID-19 and silicosis." (PMID 37278873, 2023). "The network pharmacology analysis identified seven core targets (namely, AURKA, CDK1, CCNB1, CCNB2, CCNE1, CCNE2, and TTK) of curcumol in patients with COVID-19 and LUAD." (PMID 35520289, 2022). "We identified seven core pharmacological targets of curcumol, namely, AURKA, CDK1, CCNB1, CCNB2, CCNE1, CCNE2, and TTK, in treating LUAD and COVID-19." (PMID 35520289, 2022). "The molecular network analysis using Cytoscape highlighted seven core targets of curcumol, namely, AURKA, CDK1, CCNB1, CCNB2, CCNE1, CCNE2, and TTK in COVID-19 and LUAD." (PMID 35520289, 2022). "Finally, submodule analysis showed that PRC1, KIFC1, BUB1, MCM6, CCNB2, CDKN3, and RRM2, which were hub-shared genes of silicosis and COVID-19, possessed the highest mCODE scores." (PMID 37278873, 2023).
Cirrhosis (4 papers, 2019 to 2024). A chronic disorder of the liver in which liver tissue becomes scarred and is partially replaced by regenerative nodules and fibrotic tissue resulting in loss of liver function. "The same study also identified CCNB1 and CCNB2 as DEGs and pathologically related to cirrhosis and serum albumin." (PMID 39452074, 2024). "This study revealed that PRC1, RACGAP1, CENPF, and CCNB2 could sensitively distinguish HCCfrom cirrhosis, and they may be potential targets for early HCC detection." (PMID 35445033, 2022). "Other studies have reported that the positive regulatory network of CCNB2 is involved in ubiquitination, DNA repair, and cell proliferation in non-tumor hepatitis or cirrhosis induced by HBV, suggesting that CCNB2 plays a role in HBV-related diseases." (PMID 33193629, 2020).
colorectal cancer (3 papers, 2015 to 2022). A primary or metastatic malignant neoplasm that affects the colon or rectum. "CCNB2, which is upregulated in colorectal cancer, may promote tumour cell growth by accelerating the cell cycle." (PMID 34838000, 2021). "These experiments confirmed that sites highly enriched in SOX9 binding overlap the NF-YA binding sites around the TSSs (within 500 bp of TSSs) of TOP2A, CCNB1, CCNB2 and CDK1 in colorectal cancer cells." (PMID 26040697, 2015).
psoriasis (3 papers, 2016 to 2023). An autoimmune condition characterized by red, well-delineated plaques with silvery scales that are usually on the extensor surfaces and scalp. "Previous studies of applying OYF in the treatment of psoriasis also reported an improvement effect, which might be via the regulation of keratinocyte cyclin B2, inflammatory cytokine, and chemokine release." (PMID 31929812, 2019). "Our results indicate that PSORI-CM01 may possess therapeutic potential for psoriasis by inhibiting keratinocyte proliferation through downregulation of cyclin B2." (PMID 27473420, 2016). "The results showed that CCNB2 abnormally expression maybe associated with IMQ induced psoriasis-form pathological lesion, and Psori-CM01 could inhibit the expression of CCNB2 both in the epidermis in IMQ model in vivo, and in LPS induced HaCaT cell hyper-proliferation model in vitro." (PMID 27473420, 2016). "Imiquimod induced psoriasis-form mice model was used to determine the efficacy of PSORICM-01 by assessing the improvement of hyperplasia in epidermal and dermal skin, cyclin B2 expression in skin was detected by immunochemistry." (PMID 27473420, 2016). "CCNB2 was more expressed in psoriasis-form skin especially in the mice epidermis when compared with WT group, while mice administrated with Psori-CM01 had a lower expression of CCNB2 in epidermis." (PMID 27473420, 2016).
clear cell renal cell carcinoma (2 papers, 2024 to 2025). "In renal clear cell carcinoma and thyroid cancer, elevated CCNB2 led to a general increase in immune infiltration." (PMID 38300330, 2024).
diabetes (2 papers, 2019 to 2025). "In Zhang's study (2017), CCNB2 was found to be significantly up‐regulated in diabetes mice compared with normal mice and was also the core gene in PPI network of DEGs." (PMID 30474315, 2019). "Additionally, we observed that CCNB2, XRCC2, and CENPI were elevated in BC tissues provided by patients with a diabetes history and associated with KI67 expression." (PMID 40202151, 2025).
endometrial carcinoma (2 papers, 2011 to 2023). A malignant tumor arising from the epithelium that lines the cavity of the uterine body.
glioblastoma (2 papers, 2013 to 2024). The most malignant astrocytic tumor (WHO grade IV). "Furthermore, up-regulation of CCNB2 and ASPM was detected in glioblastoma multiforme xenograft tumors and de novo glioblastoma multiforme tumors." (PMID 23282137, 2013).
Hepatitis B (2 papers, 2020 to 2022).
lymph node metastasis (2 papers, 2021). "We found no obvious correlations between CCNB2 expression and patient age (p = 0.141), tumor grade (p = 0.160), and lymph node metastasis (p = 0.247) of TNBC patients." (PMID 34354775, 2021).
membranous nephropathy (2 papers, 2016 to 2017). "In the model of membranous nephropathy report that Cdc2, cyclin B1, and cyclin B2 were increased in podocytes despite absent proliferation." (PMID 27888806, 2016).
nasopharyngeal carcinoma (2 papers, 2024 to 2025). A carcinoma arising from the nasopharyngeal epithelium. "Cyclin B2 (CCNB2), a member of the cyclin family, is an oncogene in multiple cancers, including nasopharyngeal carcinoma (NPC)." (PMID 38166895, 2024).
pancreatic ductal adenocarcinoma (2 papers, 2022 to 2024). An infiltrating adenocarcinoma that arises from the epithelial cells of the pancreas. "One very recent study conducted in human pancreatic ductal adenocarcinoma cell lines revealed that inhibition of extracellular signal-regulated kinase (ERK) led to dephosphorylation of Cdc20 and concomitant loss of APC/C target proteins securin and cyclin B (CCNB1 and CCNB2)." (PMID 39412391, 2024).
rhabdomyosarcoma (2 papers, 2021 to 2024). A rare aggressive malignant mesenchymal neoplasm arising from skeletal muscle. "Finally, our experimental results showed that MAD2L1 and CCNB2 were highly expressed in RMS cells and tissues, downregulation of MAD2L1 and CCNB2 inhibited growth of rhabdomyosarcoma cells." (PMID 34838000, 2021).
sarcoma (2 papers, 2019 to 2021). A usually aggressive malignant neoplasm of the soft tissue or bone. "CDK1, KIF11, AURKB, MAD2L1, BUB1B and CCNB2 were highly expressed in sarcoma and were markedly related to worse OS." (PMID 34838000, 2021). "Amongst the eight remaining hub genes, CDC20, CCNB2, AURKB, MAD2L1, CENPE, KIF2C, and PCNA were highly expressed and related with negative prognosis of sarcoma." (PMID 31870357, 2019).
Sepsis (2 papers, 2016 to 2025). Sepsis is defined as life-threatening organ dysfunction caused by a dysregulated host response to infection. "Conversely, the expression of CCNB2, HJURP, KREMEN1, LILRA5, and SIPA1L2 was significantly higher in the sepsis group (P < 0.05)." (PMID 40129981, 2025). "Genes including CCNB1, CCNB2 and TOP2A, as well as transcription factors like FOXM1 might be used as the novel gene therapy targets for sepsis related ARDS." (PMID 27090785, 2016).
skin cancer (2 papers, 2018 to 2023). "Nevertheless, cfDNA can provide information on copy number alterations by reflecting changes in CCNB2 and CDKN2A/B in patients with lung, brain, breast, and skin cancer." (PMID 29728089, 2018).
squamous cell carcinoma (2 papers, 2018 to 2023). A carcinoma arising from squamous epithelial cells. "Similar patterns of RHAMM and cyclin B2 staining were observed in thymus, testis, tonsil, and squamous cell carcinoma." (PMID 29765511, 2018). "In normal thymus, tonsil, and squamous cell carcinoma, RHAMM-positive and cyclin B2-positive cells were similar in number and in distribution, with the exception of the absence cyclin B2 in mitotic cells." (PMID 29765511, 2018).
thyroid cancer (2 papers, 2021 to 2024). "miR-205 inhibits the proliferation and migration of thyroid cancer cells by targeting CCNB2." (PMID 34298705, 2021). "Therefore, CCNB2 is a potential therapeutic target for thyroid cancer." (PMID 34298705, 2021).
chronic renal failure (1 paper, 2015). "Recent studies reported that the expression levels of cyclin B2 and CDK1 were increased in proliferating tubular epithelial cells from rats with chronic renal failure, and that G2/M arrest of proximal tubular epithelial cells was involved in kidney fibrogenesis." (PMID 26317775, 2015).
colon cancer (1 paper, 2019). "In this context, it is not surprising to observe that expression of CDK1, CDK2, and cyclin B2 (CCNB2), which have close functional interactions with an oncogenic protein CKS1B, was significantly increased in colon cancer samples in the TCGA data set." (PMID 31717435, 2019).
Ductal carcinoma in situ (1 paper, 2017). "We thus concluded that Five genes: CDK1, CCNB2, MAD2L1, PPARG, ACACB were finally identified to participate in the regulation and serve as potential diagnosis signatures in in Ductal carcinoma in situ." (PMID 28977921, 2017).
endocrine cancers (1 paper, 2023). "Some of the most upregulated genes in the metastatic tumours are the pituitary tumour-transforming gene (PTTG1), a marker of invasion in many tumour types including endocrine cancers and the pro-proliferative cyclin B2 CCNB2." (PMID 38124114, 2023).
endometriosis (1 paper, 2024). The growth of functional endometrial tissue in anatomic sites outside the uterine body. "This suggests that in the pathomechanism of endometriosis, cyclin B1’s function is complemented by the overexpression of cyclin B2." (PMID 38398227, 2024). "In contrast, in endometriosis tissue, genes such as CDC20, CCNB1, and CCNB2 played a central role." (PMID 38398227, 2024).
fibrosis (1 paper, 2024). the formation of excess fibrous connective tissue in an organ or tissue in a reparative or reactive process. "To date, there have been limited reports on the relationships between CCNB2, NCAPG, KIF20A, KIF11, and BUB1B with SSc or fibrosis." (PMID 38343538, 2024).
Hepatitis (1 paper, 2020). Inflammation of the liver.
Hyperglycemia (1 paper, 2025). An increased concentration of glucose in the blood. "Hyperglycemia treatment elevated the expression levels of CCNB2, XRCC2, and CENPI in BC cells, which correlated with increased cell proliferation and mobility." (PMID 40202151, 2025).
ischemic stroke (1 paper, 2021). A stroke disorder caused by obstruction of blood flow to the brain, due to thrombotic (local blood clot formation) or embolic (due to a blood clot or other material traveling from another site) event. "Ultimately, seven downregulated hub genes (including Mki67, Cdk1, Tpx2, Cenpf, Ccnb2, Prc1, and Top2a) were identified as key genes regulated by EA treatment in ischemic stroke by PCR validation." (PMID 34566862, 2021).
laryngeal squamous cell carcinoma (1 paper, 2016). A squamous cell carcinoma that arises from the larynx. "In this study, we analyzed the expression profile of four genes (CCNA2, CCNB1, CCNB2, and CDK1) in laryngeal squamous cell carcinoma (LSCC) cell lines and tumor samples." (PMID 26912061, 2016). "In the current study, we have analyzed the expression pattern of group of genes —CCNB1, CCNB2, CCNA2, and CDK1 in laryngeal squamous cell carcinoma." (PMID 26912061, 2016).
leukemia (1 paper, 2021). A malignant (clonal) hematologic disorder, involving hematopoietic stem cells and characterized by the presence of primitive or atypical myeloid or lymphoid cells in the bone marrow and the blood. "We utilized the data of gene expression profiling in samples with higher E2F1 expression and identified the genes associated with cell cycle progression (CCNA2, CCNE2, CCNB1, CCNB2 and, importantly, CCNE1) which were also found to be upregulated in leukemia cells exposed to DBF." (PMID 34564151, 2021).
liposarcoma (1 paper, 2007). A usually painless malignant tumor that arises from adipose tissue. "Genes highly expressed in the dedifferentiated/pleomorphic liposarcomas included cell-cycle genes like CCNA2, CCNB2, CDC2, KIFC1, KIF23 and PTTG1, motility genes like AMFR, ANXA1, CKB, CNN2 and FN1 and homeostasis-related genes." (PMID 17359542, 2007).
liver fibrosis (1 paper, 2023). "Subsequently, the expression of Anln, Hmmr, Tpx2, Ccnb1, and Ccnb2 was measured in activated hepatic stellate cells (HSCs), which have been shown to become myofibroblast-like cells known to contribute to the progression of liver fibrosis through the deposition of extracellular matrix proteins." (PMID 37566034, 2023).
low grade glioma (1 paper, 2022). A grade I or grade II glioma arising from the central nervous system. "However, the correlation between prognosis of low-grade glioma (LGG), CCNB2, and tumor infiltrating lymphocytes is not clear." (PMID 34908101, 2022).
Lynch syndrome (1 paper, 2013). An autosomal dominant hereditary neoplastic syndrome characterized by the development of colorectal carcinoma and a high risk of developing endometrial carcinoma, gastric carcinoma, ovarian carcinoma, renal pelvis carcinoma, and small intestinal carcinoma. "Lynch syndrome tumors showed up-regulation of 1129 genes, e.g. genes involved in G1/S transition (CCNE, CCNH, E2F2 and CDK2), DNA replication (CDC45, RPA1, RFC5, MCM4 and POLD3) and chromosomal organization and mitosis (CCNB2, MLF1IP, CASC5, KIF2C and PLK4), which is in line with previous findings." (PMID 23951239, 2013).
memory impairment (1 paper, 2021). "A previous result showed that Cyclin B2 and CDK1 increased in the condition of neurodegeneration and memory impairment." (PMID 34561612, 2021).
Obesity (1 paper, 2021). Accumulation of substantial excess body fat. "Therefore, we assume that abnormal expression of Cyclin/CDKs results in the low frequency of polyploidy in the brain with obesity because circTshz2-2 suppression reduced the expression of Cyclin B2 and CDK1 in the brain cortex and hippocampus of obese mice." (PMID 34561612, 2021). "First, we observed higher Cyclin B2 and CDK1 expression in the cortex and hippocampus of obese mice than wild-type mice, indicating that G2/M checkpoint proteins increase under the condition of obesity-induced neurodegeneration." (PMID 34561612, 2021).
osteoporosis (1 paper, 2022). A condition of reduced bone mass, with decreased cortical thickness and a decrease in the number and size of the trabeculae of cancellous bone (but normal chemical composition), resulting in increased fracture incidence. "For example, CCNB2 as hub nodes plays an essential role in regulating bone remodeling of osteoporosis." (PMID 35846320, 2022).
papillary renal cell carcinoma (1 paper, 2019). A rare subtype of renal cell carcinoma, arising from the renal tubular epithelium and showing a papillary growth pattern, which typically manifests with hematuria, flank pain, palpable abdominal mass or nonspecific symptoms, such as fatigue, weight loss or fever. "We identified 5 mRNAs that are associated with the survival of patients with papillary renal cell carcinoma,namely CCNB2, IGF2BP3, KIF18A, PTTG1, and BUB1 in the training set." (PMID 30822312, 2019). "In general, the 5-mRNA (CCNB2, IGF2BP3, KIF18A, PTTG1, and BUB1) were identified and validated, which can predict papillary renal cell carcinoma patient survival." (PMID 30822312, 2019).
premature ovarian failure (1 paper, 2024). "Sufficient pre-MPF needs to be prepared by CCNB2 to enable meiotic re-entry, and CCNB2 depletion leads to ovulation of immature oocytes and premature ovarian failure." (PMID 38300330, 2024).
prostatic intraepithelial neoplasia (1 paper, 2020). "Researchers found that survivin plays an important role in the conversion process of prostatic intraepithelial neoplasia to adenocarcinoma CCNB2 is linked to the process of transition from the G2 to the M phase." (PMID 32266115, 2020).
renal cell carcinoma (1 paper, 2021). "A previous study found that 10 cell proliferation genes, including BUB1, CCNB2, and CDK1, could act as indicators for response to immune checkpoint inhibitors in PD-L1 negative renal cell carcinoma." (PMID 34440557, 2021).
seminoma (1 paper, 2018). A radiosensitive malignant germ cell tumor found in the testis (especially undescended), and extragonadal sites (anterior mediastinum and pineal gland). "To evaluate this possibility, we examined RHAMM expression in classical seminoma and spermatocytic tumor, and compared it with that of cyclin B2." (PMID 29765511, 2018). "Cyclin B2, in comparison, showed lower expression in spermatocytic tumors than in some cases of seminoma, the opposite of RHAMM expression." (PMID 29765511, 2018). "While RHAMM showed stronger expression in spermatocytic tumors than in any of the seminomas tested, cyclin B2 was only weakly expressed in spermatocytic tumors." (PMID 29765511, 2018). "However, the staining patterns of RHAMM and cyclin B2 in seminoma and spermatocytic tumor were different." (PMID 29765511, 2018).
testicular germ cell tumor (1 paper, 2025). A germ cell tumor arising from the testis. "It has been shown that the aberrant development of PGCs and testicular germ cell tumors can result from the disruption in CCNB1 and CCNB2 genes." (PMID 41009526, 2025).
thyroid (1 paper, 2012). "Intriguingly, Pax8 modulates the expression of several genes involved in carcinogenesis and thyroid malignancies (phosphatidyl-inositol/insulin and MAPK pathways) and cell cycle processes (CDKN2BCCNB1 and CCNB2, among others)." (PMID 22531031, 2012).
trisomy 18 (1 paper, 2021). Trisomy 18 is a chromosomal abnormality associated with the presence of an extra chromosome 18 and characterized by growth delay, dolichocephaly, a characteristic facies, limb anomalies and visceral malformations. "Nonetheless, our study reveals important molecules that may be associated with the development of trisomy 18: CCNB2 and MCM3 may be vital." (PMID 34193281, 2021).